TNF (tumor necrosis factor)
Diseases named in the same sentence as TNF in open-access papers (continued):
Sharing a sentence is not in itself a finding about the gene and the disease.
infectious disease (continued). "MSCs also modulate the early stages of inflammation by secreting IL-1 receptor antagonist, in that way blunting the influences of IL-1 and TNF-α on stimulating both aseptic and infectious inflammation." (PMID 37470690, 2023). "Recent research on immune responses to infectious disorders has uncovered and characterized a vital function for multifunctional T cells that co-express IL-2, TNF-α, and IFN-γ." (PMID 36960295, 2023). "The WBC count, and CRP, PCT, TNF‐α, and IL‐6 levels are the most common clinical indicators to assess infectious diseases." (PMID 37102655, 2023). "TNF-α is a multifunctional cytokine that plays an important role in the pathology of many infectious diseases through its involvement in immune regulation and inflammation." (PMID 36287932, 2022). "TNF-α, as a proinflammatory cytokine, plays an important role in the clinical manifestation of various autoimmune conditions and infectious diseases." (PMID 36052277, 2022). "It is also useful for prevention of septic infection, while anti‐IL‐6 antibody and TNF‐α blocker sometimes aggravate infectious diseases because of oversuppression of the immune system." (PMID 35588199, 2022). "Some of these had been previously associated to a worse prognosis in HIV and other infectious diseases, or related to inflammatory status (IL-6, CD14, CD163, IRAK-M, and TNFα)." (PMID 34211989, 2021). "The findings of our meta-analyses pose questions about the application of anti-TNFα use, especially in infectious disease patients." (PMID 34790122, 2021). "IL-22 also contributes to the immune response against various infectious diseases of the gut-lung-skin barrier and exhibits pro-inflammatory roles by enhancing the effects of tumor necrosis factor-alpha (TNF-α), and by activating various other cytokines." (PMID 34072930, 2021). "Since TNF has been shown to play a major role in numerous inflammatory and infectious diseases, knowledge of the precise impact of TNF‐induced inflammation and cell death on the cellular and pathophysiological level are of major importance." (PMID 32914580, 2020). "While co-production of IFN-γ, TNF-α and IL-2 by T cells is frequently investigated, reports on these cytokines in combination with IL-17A in the context of infectious diseases are rather scarce." (PMID 33584671, 2020). "The TNF-α treatment of A549 cells enhanced the expression of multiple genes involved in several pathways, affecting inflammatory signaling, infectious disorders, and cellular processes." (PMID 32246052, 2020). "And, the inflammatory process extensively mediated by the TNF signaling pathway also had a certain regulatory effect on the occurrence and development of infectious diseases." (PMID 33292385, 2020). "Tumor necrosis factor-α (TNF-α) is a proinflammatory cytokine associated with autoimmune and infectious diseases." (PMID 31409832, 2019). "It has been previously reported that, in the veterinary field and particularly in bovine infectious diseases, numerous bacteria such as Escherichia coli and Mycoplasma bovis can induce the prompt release of TNF-α." (PMID 30819151, 2019). "For example, the MCI–T2D network was enriched in genes associated with infectious diseases and inflammation, including hepatitis B and C, Epstein–Barr virus infection, HTLV-1 infection, Kaposi’s sarcoma-associated herpesvirus, NFKB, and TNF signaling pathways." (PMID 31849586, 2019). "Additional studies are needed in order to clarify the effect of such compounds as SB and their role as adjuvant antioxidant, antimicrobial, and local immune response modulators (TNF-α) in the treatment of infectious diseases." (PMID 31687075, 2019). "Th1 cells and their cytokines, including IFN-γ and TNF-α, play essential roles in the biochemical responses to infectious disease pathogens and inflammation." (PMID 31686983, 2019).
infectious disease (continued). "It is also puzzling that aberrant elevation of TNFα production elicits tissue damage in many inflammatory and infectious diseases including septic shock, in which there are few known genetic defects in or pharmaceutical inhibitors of the IKK signaling pathway." (PMID 29795446, 2018). "It is also useful for prevention of septic infection, while anti-IL-6 antibody and TNF-α blocker sometimes aggravate infectious diseases." (PMID 29699567, 2018). "The inflammatory cytokine TNFα plays a crucial role in the pathology of many inflammatory and infectious diseases." (PMID 29795446, 2018). "For sTNF-RII, that has mainly an anti-inflammatory effect by preventing circulating TNF-α from activating its cell bound receptors, there is a lack of available data on its dynamics in pregnant women with other infectious diseases." (PMID 29255607, 2017). "The depressive signs that occur in infectious diseases are related to the secretion of cytokines IL-1, IL-6 and TNFα." (PMID 28278190, 2017). "TNF-α has been shown to play a dual role, beneficial and deleterious effect for the promotion or inhibition of infectious diseases." (PMID 28479926, 2017). "Initial experiments were performed to determine the effect of TNF-α treatment at and above concentrations found in the plasma of patients with diverse inflammatory and infectious diseases." (PMID 27603666, 2016). "Given the broad ramifications of glutamate-induced excitotoxicity in infectious and non-infectious disease, these additional layers of information about TNF provide insights with widespread therapeutic implications." (PMID 27596607, 2016). "TNF is known to be involved in immunological response and required for defense against infectious diseases." (PMID 27080559, 2016). "This led to a collaboration that generated the then novel, but now widespread, argument that enhanced TNF generation is central to innate immunity, whereas its excessive production triggers major infectious disease." (PMID 26221543, 2015). "Tumor necrosis factor alpha (TNF-α) is a cytokine which plays opposing roles in the context of infectious disease pathogenesis." (PMID 25999670, 2015). "As has been reviewed, the logic of the pathogenesis of certain infectious diseases being driven by TNF now encompasses essentially all such conditions." (PMID 26221543, 2015). "Polyfunctional T cells have been associated with protective immunity on the grounds that the number of T cells producing IFNγ, IL-2, and/or tumor necrosis factor-α (TNFα) is correlated with vaccine induced protection in models of infectious diseases." (PMID 25379038, 2014). "TNF-α is a proinflammatory cytokine involved in several processes such as inflammation and control of infectious diseases." (PMID 24563803, 2014). "It has been proposed that polyfunctional T cells, particularly those producing IFN-γ, TNF-α, and IL-2, correlate with protection and control of infectious diseases." (PMID 23762485, 2013). "The human and murine model studies revealed that the outcome in infectious diseases is influenced by TNF-α." (PMID 22276993, 2012). "The TNF-alpha gene is located in an important region of the MHC and its polymorphisms are associated with many parasitic and infectious diseases such as cerebral malaria and leishmaniasis." (PMID 21408088, 2011). "For example, since TNF-α is a critical component of immunity, infectious disease is a primary concern during TNF-α therapy." (PMID 20827314, 2010). "Polymorphisms in the genes encoding TNF and LTA appear to contribute to infectious disease susceptibility and infection." (PMID 20668555, 2010). "A major response to infectious disease is a cytotopathic effect resulting from activation of this pathway, and the production of TNF-α has been shown to correlate with a cytopathic effect in infected cells." (PMID 19412525, 2009).
infectious disease (continued). "Tumour Necrosis Factor (TNF) is involved in multiple inflammatory and immune responses and plays an important role in the pathogenesis of many infectious diseases including P. falciparum malaria." (PMID 18194515, 2008). "TNF-α levels are usually low in seminal plasma, but they tend to increase in inflammatory and infectious diseases." (PMID 21279185, 2008). "The five TNF-α inhibitors have high signals in mycobacterial infectious disorders." (PMID 40371340, 2025). "Even though some protein levels might be masked by drug treatment, data analysis showed high levels of INF-Υ, IL-10 and TNF-α in the infectious disease group, critical cytokines for the immune response against viruses and bacteria." (PMID 39328992, 2024). "CD16 monocytes, known for TNF α production upon LPS stimulation, may undergo expansion during acute inflammation and infectious diseases, yet their precise function remains elusive." (PMID 38459548, 2024). "In addition, macrophages respond to multiple activators such as LPS, TNFα, and IFNγ in infectious diseases." (PMID 37569508, 2023). "TNF has been identified as a key regulator of the inflammatory response in infectious diseases." (PMID 36674828, 2023). "In order to show that EVs from GES-1 infected with H. pylori cells participate in the spread of infectious disease, the mRNA levels of proinflammatory cytokines TNF-α, IL-8, IL-6, IL-1β and IL-23, in GES-1 and AGS cells stimulated for 24 h with EVHp- or EVHp+ were measured by RT-qPCR." (PMID 36313672, 2022). "Other work has revealed targeting TNF-α can protect mice against some, but not all, strains of Dengue virus and against hemophagocytic lymphohistiocytosis-like disease induced by infectious disease, possibly implicating TNF-α as a broad spectrum target for multiple infectious diseases." (PMID 35587473, 2022). "TNF-α and IL-6 are common inflammatory factors, and their blood levels show corresponding changes when inflammation occurs, and increases in its levels can be seen in various infectious diseases and have significant signs of illness in HP-infected patients." (PMID 35414799, 2022). "We believe that further research is warranted to completely understand these mechanisms and examine the role of clindamycin in inhibiting concentrations of TNFα in humans to pave the way for other potential applications in the treatment of non-infectious diseases." (PMID 35630085, 2022). "TB is an infectious disease with significant global mortality, characterized by increased ROS production and subsequent lipid peroxidation and tissue damage mediated by inflammatory cytokines, especially TNF-α." (PMID 34239993, 2021). "Increased levels of TNF-α may therefore confer increased protection against infectious diseases (particularly those that require close individual contact)." (PMID 32116590, 2020). "Feeding DON for a long time resulted in lower TNF-α in plasma, which indicated that DON could affect immune function, therefore, leading to a higher infectious disease susceptibility in chickens." (PMID 31480205, 2020). "Moreover, patients treated with TNF alpha inhibitors are more likely to develop infectious diseases." (PMID 31915712, 2019). "We speculated that the elevated levels of TNF in BPSM1 mice may also impact on the outcomes of infectious diseases." (PMID 30107066, 2019). "The authors also highlighted that therapeutic strategies that increase the IL-10 and reduce the concentration in TNF-α could be used as adjuvants for treatment of such tissue injuries, as well as for infectious diseases." (PMID 30564201, 2018). "Specific blockade of substantial BAD release from the cytoskeleton to the cytosol may prevent or at least reduce TNFα cytotoxicity in inflammatory and infectious diseases." (PMID 29795446, 2018).
infectious disease (continued). "Given the importance of TNFα cytotoxicity in the pathologies of many inflammatory and infectious diseases, our finding is likely to have broad implications in prevention and treatment of inflammatory and infectious diseases." (PMID 29795446, 2018). "With their collaboration in assaying TNF, we began to develop our then novel view that infectious disease is caused not directly by the invading pathogen, but by what were effectively the side effects of the host’s over-exuberant innate immune response to it." (PMID 28451786, 2017). "TNF was recognized, and named, as an endogenous tumor killing agent, and 6 years later, its wider biological importance began to be appreciated through its roles in innate immunity and the pathogenesis of infectious disease (, reviewed in 2004)." (PMID 27596607, 2016). "Clearly, understanding advances in infectious diseases and inflammation would take neurologists directly into the world of basic TNF biology and thence how the corrupting effects of its excessive poststroke production in the brain would lead to neurodegenerative disease." (PMID 26221543, 2015). "In conclusion, we identified genes that act directly within the GR signal transduction pathway as well as GR-associated genes including TNF and IFNG that have both been associated with prenatal iAs or Cd exposure in humans and established to play a role in infectious disease." (PMID 25479081, 2014). "Thus, TNF represents an additional GR-related protein and gene target for future mechanistic investigations relating environmental contaminant and infectious disease relationships." (PMID 25479081, 2014). "The decreasing level of TNF-α is one of the possible impairment of immune function after chronic DON exposure in poultry and could thus increase the susceptibility to infectious diseases." (PMID 23628787, 2013). "Thus, an interest exists in investigating the use of inhibitors of TNF-α in the treatment of infectious diseases." (PMID 24373231, 2013). "The reduction of TNF-α in the plasma after chronic feeding of DON in this study is a significant indicator that DON can impair immune function and increase susceptibility to infectious diseases." (PMID 23628787, 2013). "Our analysis further delineated peripheral transcripts, including the infectious disease susceptibility gene CISH, encoding cytokine inducible SH2-containing protein, and EBI3, encoding Epstein-Barr virus induced 3, putatively modulated by TNFα signaling." (PMID 24236088, 2013). "IFN-γ, TNF, and IL-2 are analyzed most often to assess cellular immunity to infectious diseases." (PMID 20520820, 2010). "The -204 locus was a new discovered SNP site of TNF-α promoter region and its role in infectious diseases might need further study." (PMID 18312678, 2008). "Moreover, increased circulating levels of TNF and functionally similar cytokines have been measured in the serum very soon after onset of illness in virtually all those infectious diseases in which it has been sought." (PMID 17029647, 2006). "Hence, ADAM17 might be crucial in the immunopathogenesis of several inflammatory disorders and infectious diseases, especially those that depend on TNF signaling and a balanced immune response for protective immunity." (PMID 38881671, 2024). "We propose that high progesterone levels facilitate living in large social groups and that high baseline serum levels of TNF-α may occur as a consequence of social interactions and confer some protection from communicable diseases that accompanies living in close proximity to others." (PMID 32116590, 2020). "As the main reason for tooth loss, oral bacterial infectious diseases are associated with a chronic low-grade inflammation, which can upregulate inflammatory biomarkers including C-reactive protein (CRP), tumor necrosis factor alpha (TNF-alpha), and interleukin-6 (IL-6)." (PMID 32649678, 2020).
infectious disease (continued). "Since TNF-α acts as a promoter of leucocyte adhesion to the endothelium, the SB might be beneficial as antimicrobial, local immune response, and oxidative status modulator in the treatment of infectious diseases." (PMID 31687075, 2019). "However, exorbitant or uncontrolled TNF-α activity may also drive pathology and disease symptoms in many infectious diseases." (PMID 25999670, 2015). "Thus, the roles of TNF-α gene in infectious diseases should be further studied." (PMID 18312678, 2008). "The immune-modulatory effects of microbial metabolites also extend to infectious diseases, which influence vital markers such as cytokines, C-reactive protein (CRP), and tumor necrosis factor-alpha (TNF-α)." (PMID 39857684, 2025). "It's worth noting that the five TNF-α inhibitors have high ROR and IC value in mycobacterial infectious disorders." (PMID 40371340, 2025). "However, a pathological increase in TNF-α level will have a counterproductive effect, damage the body's immune function, intensify the level of inflammatory activity, and are tightly connected to the emergence and progress of multiple inflammatory or infectious diseases in the body." (PMID 38996725, 2024). "Many inflammatory biomarkers including CRP, Cytokines i.e. Tumor necrosis factors (TNF), interleukin-6 (IL-6) and ESR aid in diagnosis of complex inflammatory and infectious disorders but lack specificity." (PMID 38681106, 2024). "In the LPS-induced infectious disease model, there was a significant increase in chemokines (CCL2), proinflammatory cytokines (IL1β, IL6, TNFα), and a marked decrease in MCH." (PMID 38654385, 2024). "Inflammatory cytokines, such as interleukin-1 (IL-1), interleukin-6 (IL-6), and tumor necrosis factor-alpha (TNF-α), play a significant role in the pathogenesis of infectious diseases." (PMID 38305363, 2024). "Tumor necrosis factor (TNF), a crucial proinflammatory cytokine primarily secreted by macrophages, plays a pivotal role in the progression of numerous infectious disorders." (PMID 39301021, 2024). "In human infectious diseases, GZMK can activate the protease activated receptor-1 (PAR-1) in endothelial cells and induce the production of inflammatory cytokines (TNF-α, IL-1, and IL-6)." (PMID 36199375, 2022). "For example, interleukin 1-β (IL-1β), IL-6, IL-8, as well as tumor necrosis factor alpha (TNF-α) elicit NETs and thus may represent crucial immunoregulatory effector molecules of the host that presumably modulate NETosis during specific inflammatory or infectious diseases." (PMID 35237275, 2022). "Tumor necrosis factor- α (TNF-α) is a potent proinflammatory cytokine that plays role in the pathogenesis and development of various infectious diseases." (PMID 33766078, 2021). "However, the observation that cIAPs limit TNF-mediated apoptosis and that Smac-mimetics sensitize cells to TNF induced cell death led to the idea that these drugs might also be used for therapeutic applications in infectious diseases." (PMID 32824616, 2020). "The predicted interacting signaling pathways under “Infectious Diseases: Viral” category primarily include Ras, MAPK, PI3K-Akt, cAMP, Rap1, ErbB, Jak-STAT, Sphingolipid, TNF, FoxO, and Wnt signaling pathways." (PMID 30275399, 2018). "Furthermore, the link established here between TNF and the development of BM CD4+ T cells with potential to irreversibly impact on LT-HSC function may be of importance in other non-infectious diseases where TNF production and hematological abnormalities co-exist." (PMID 28671989, 2017). "IFN-γ has often been used as a single readout for Th1 responses, but recent studies of other infectious diseases have emphasized the importance of polyfunctional T cells co-producing IL-2, IFN-γ and TNF-α." (PMID 20505822, 2010).